IL6 (interleukin 6)
Diseases named in the same sentence as IL6 in open-access papers (continued):
Sharing a sentence is not in itself a finding about the gene and the disease.
acute pancreatitis (continued). "Previously, a beneficial effect of PTX treatment was demonstrated in rats submitted to acute pancreatitis and showed that PTX very effectively decreased TNF-alpha and IL-6 production under this condition." (PMID 24991532, 2014). "Discriminant analysis was performed to further investigate the value of serum BAFF, IL-6, CRP, PCT, and leukocyte counts measured at the day of admission to predict a severe course of acute pancreatitis (sNPoD)." (PMID 23342125, 2013). "As with IL-6, TNF-α represents a major determinant of the systemic progression and end-organ damage such as acute lung injury in acute pancreatitis." (PMID 23110041, 2012). "The earliest difference between acute pancreatitis (BPD-ligated) and sham operated groups, was the early rise of IL-6 in plasma." (PMID 23110041, 2012). "Although we measured only IL-6 and TNF, other inflammatory mediators known to play a critical role in acute pancreatitis and MODS include TNFa, IL-1b, IL-6, IL-8, platelet-activating factor, and IL-10." (PMID 20015376, 2009). "Taken together, IL-6 and Ang-2 should not be viewed as competing markers but as complementary indicators that capture sequential aspects of the pathophysiology of severe acute pancreatitis." (PMID 41590239, 2026). "Across diverse populations and sampling windows, IL-6 demonstrated the ability to discriminate between severe and non-severe acute pancreatitis with moderately high accuracy." (PMID 41590239, 2026). "Based on this observation, we evaluated serum IL-6 and OSM in a mouse model of acute pancreatitis." (PMID 40560328, 2025). "An essential inflammatory cytokine involved in the pathophysiology of acute pancreatitis is tumor necrosis factor (TNF)-α, along with IL-1β, IL-6, IL-8, and IL-10 as the most relevant biomarkers, which damages acinar cells directly and causes necrosis, inflammation, and edema." (PMID 40150718, 2025). "Furthermore, in an acute pancreatitis mouse model, 1,8‐cineole administration resulted in lower cytokine levels of TNF‐α, IL‐1β, and IL‐6, reflecting the results found with thalidomide, a TNF‐α inhibitor." (PMID 40719271, 2025). "Conclusions the Bedside Index of Severity in Acute Pancreatitis (BISAP) and severity classification of the revised Atlanta classification system, IL-6 and VEGF, determined 48 h after hospitalization, were the two cytokines consistently elevated in the most severe patients." (PMID 38673560, 2024). "Additionally, emerging biomarkers such as interleukin-6 (IL-6) and procalcitonin (PCT) have shown promise in early severity stratification of acute pancreatitis." (PMID 39011189, 2024). "In acute pancreatitis patients, high serum or plasma levels of IL-6 and IL-8 were observed in severe versus non-severe cases." (PMID 36671034, 2023). "Although epidural bupivacaine decreased plasma interleukin-6 in a rat model of acute pancreatitis, there was no between-group difference in plasma interleukin-6 over time in our trial." (PMID 37259157, 2023). "Clinical evidence showed that UTI had a significant effect on inflammatory biomarkers such as C-reactive protein (CRP), interleukin-6 (IL-6), and tumor necrosis factor-alpha (TNF-α), as well as reduced and prevented MODS and lowered mortality in acute pancreatitis." (PMID 35634310, 2022). "Studies suggested that calycosin could diminish the levels of TNF-α, IL-6, and IL1B in mice with acute pancreatitis." (PMID 35227280, 2022). "Therefore, preventing the release of inflammatory factors IL-6, IL1-β, and TNF-alfa is an important research direction to prevent the progression of acute pancreatitis." (PMID 36611865, 2022). "The use of panaxadiol saponins in severe acute pancreatitis can inhibit the expression of TNF-α and interleukin-6 (IL-6), reduce blood concentration, improve microcirculation, and upregulate the expression of AQP1 in lung tissue, thereby reducing pulmonary edema and lung injury." (PMID 36532729, 2022).
acute pancreatitis (continued). "Besides, it also investigated the effect of XCHD on the generation of IL-6, IL-1β, and TNF-α in an LPS-induced acute pancreatitis model." (PMID 33824873, 2021). "The exact mechanism for acute pancreatitis with TCZ is unknown, but it may be due to hypertriglyceridemia and IL-6 inhibition." (PMID 34552181, 2021). "Besides, in a mice model of acute pancreatitis, low-methoxyl PEC was found to downregulate TNF-α, IL-1β and IL-6 mRNA levels in ileal and colonic tissue, leading to the recovery of acute pancreatitis-associated disorder of the intestinal barrier." (PMID 32276396, 2020). "In this study, we investigated whether DHA reduces ROS levels and inhibits IL-6 expression via Nrf2 signaling in pancreatic acinar (AR42J) cells stimulated with cerulein, as an in vitro model of acute pancreatitis." (PMID 33158207, 2020). "Lack of PGC-1α during pancreatitis specifically upregulates IL-6, a reliable marker of severity in acute pancreatitis." (PMID 32215168, 2020). "Compared to the untreated group, the administration of rat foetal membrane-derived mesenchymal stem cells (rat FM-MSC) into the rat penile vein after the induction of severe acute pancreatitis reduced the serum levels of proinflammatory cytokines (TNF-α and IL-6)." (PMID 29743979, 2018). "Additionally, this approach gave us the opportunity to evaluate BAFF as compared to CRP, IL-6, PCT, and number of leucocytes as a predictor of severity and course of acute pancreatitis." (PMID 23342125, 2013). "Investigations into the origin of these peptides have demonstrated that intra-pancreatic cytokine levels reach concentrations several-fold higher than corresponding systemic levels, thus providing evidence that IL-1, IL-6 and TNF-α are produced within the pancreas during acute pancreatitis." (PMID 23181131, 2012). "However, there are no studies about polymorphism in the IL6 gene and its association with the concentration of SOD isoenzymes and total SOD activity during acute pancreatitis." (PMID 35205334, 2022). "However, in severe acute pancreatitis, there is extensive acinar cell injury, which leads to neutrophil, monocyte, and lymphocyte activation, and this results in the secretion of plenty of inflammatory mediators such as TNF-α, IL-6, and IL-10." (PMID 35296066, 2022). "Orlistat was shown to decrease IL-6 and TNFα in diabetic patients, and to reduce systemic inflammation and pancreatitis-induced death in obese (ob/ob) mice as measured by a lower mortality incidence and decreased serum levels of TNFα, MCP-1 and IL-6 in an acute pancreatitis mouse model." (PMID 33440724, 2021). "However, in our series, IL-6 did not predict acute pancreatitis or its severity at 4 hours." (PMID 27642079, 2016). "In a prospective study of 175 patients divided into mild and non-mild acute pancreatitis according to the Atlanta classification, CRP and IL-6 combined demonstrated good discriminative capacity with an area under the curve of 0.803." (PMID 31210778, 2019). "When considering IL-6, these results come as no surprise, but there are very few studies that include VEGF and its role in acute pancreatitis patients; therefore, we can conclude that our study may constitute a milestone in the development of possible new markers for assessing the severity of AP." (PMID 38673560, 2024). "Using acute pancreatitis as a model for severe systemic inflammation without confounding factors like infectious agents, autoimmune processes, or malignant processes, we were able to show for the first time that BAFF behaves like an acute phase protein with a kinetic similar to IL-6 or PCT." (PMID 23342125, 2013).
delirium (174 papers, 2008 to 2026). A disorder characterized by confusion; inattentiveness; disorientation; illusions; hallucinations; agitation; and in some instances autonomic nervous system overactivity. "Admittedly, NPAR is a non-specific marker of systemic inflammation, and more specific cytokines like IL-6 have been linked to delirium." (PMID 41592020, 2026). "Clinical data indicate that liver disease patients with elevated preoperative IL-6 levels have more than double the risk of developing postoperative delirium (OR > 2.0)." (PMID 41332466, 2025). "Previous studies have shown that higher levels of IL-6 in preoperative plasma are associated with postoperative delirium, which is consistent with our research findings." (PMID 41229511, 2025). "Elevated levels of IL-6 in preoperative CSF are associated with the occurrence of postoperative delirium." (PMID 41018204, 2025). "C-reactive protein (CRP) and pro-inflammatory cytokines such as IL-6 have been consistently linked to the occurrence and duration of delirium in critically ill and postoperative patients." (PMID 41459337, 2025). "Older adults with higher perioperative plasma interleukin-6 (IL-6) and IL-8 are at greater risk of developing postoperative delirium." (PMID 41226311, 2025). "Of note, Il-8 levels are higher in the days before delirium onset, whereas IL-6 has been associated with hyperactive delirium." (PMID 39860413, 2025). "We also used the high-throughput, aptamer-based SomaScan proteomics platform to identify high preoperative (PREOP) chitinase-3-like-protein-1 (CHI3L1/YKL-40) and high postoperative day 2 (POD2) IL-6 as risk and disease markers of postoperative delirium." (PMID 39199312, 2024). "During the early postoperative period, an increase in peripheral blood IL-6 concentration is associated with a higher risk of postoperative delirium." (PMID 38302882, 2024). "Notable among these are IL-6 and IL-8, which have been linked to delirium in older surgical patients and been proposed as potential biomarkers for it in several prior studies." (PMID 37156856, 2023). "High serum IL-6 or C-reactive protein (CRP) levels were reported to increase the risk of postoperative delirium (POD) in three meta-analyses of cohort or case–control studies." (PMID 37649721, 2023). "Only four proteins were associated with delirium in both age groups: IL-8, IL-6, leukemia inhibitory factor (LIF), and asialoglycoprotein receptor 1 (ASGR1)." (PMID 37156856, 2023). "Twenty-two studies investigated the association of IL-6 and delirium, which made it the most investigated biomarker." (PMID 37360340, 2023). "A meta-analysis has shown a modest association between delirium and serum interleukin (IL)-1 receptor antagonist and IL-6." (PMID 37649721, 2023). "It was noted that IL-6 was specifically associated with the hyperactive form of delirium, whereas IL-8 was highest in the days leading up to the onset of delirium." (PMID 38131687, 2023). "IL-6 and IL-8, as mentioned, have been strongly associated with delirium in older subjects previously." (PMID 37156856, 2023). "Among the pro-inflammatory cytokines, TNFα is upstream of 17 of the 32 CSF delirium-associated proteins, IFNγ has a potential connection to 15/32 CSF proteins, IL-6 is upstream of 10/32 proteins, and IL-10 is upstream of 8/32 proteins." (PMID 37759795, 2023). "Twenty-two studies investigated the association between IL-6 serum concentration at hospital admission and delirium during hospitalization." (PMID 37360340, 2023). "Peripheral IL-6-associated microglial QUIN elevations in the BLA contributed to cognitive dysfunction in the model of postoperative delirium." (PMID 36160165, 2022). "It has been reported that postoperative elevation of peripheral C-reactive protein (CRP) and interleukin 6 concentrations is associated with higher risks of postoperative delirium." (PMID 35294925, 2022).
delirium (continued). "This is concordant with clinical studies that have found that high levels of IL-6 preoperatively were significantly associated with postoperative delirium in patients admitted for elective and emergency surgery." (PMID 36030220, 2022). "We suppose that delirium is associated with increased proinflammatory cytokines (such as IL-6 and TNF-α), which leads to inappropriate activation of peripheral CD4+ T cells and exacerbation of neuroinflammation in the brain, with BBB disruption." (PMID 36118695, 2022). "Increased IL-6 signaling has been associated with a diversity of neuropsychiatric impairments including delirium and is frequently elevated in individuals with acute encephalopathy and VILI." (PMID 36100846, 2022). "Comparing the findings from this review to other causes of delirium makes clear that in delirium from other causes mostly biomarkers regarding inflammatory pathways are involved (e.g., IL-6, CRP, Corsitol, TNF-alpha)." (PMID 36230916, 2022). "In this case, finding seems to suggest that, during differentiation, the detrimental effect on neurogenesis and apoptosis caused by the high IL6 concentrations in serum from delirium patients is mediated by production of IL13." (PMID 36195636, 2022). "We found that in AAD patients undergoing surgery, plasma IL-6 measured at several timepoints was associated with delirium." (PMID 34044881, 2021). "Elevated plasma concentrations of TNF-α, IL-6 and IL-8 were reported to be associated with delirium." (PMID 34425856, 2021). "So on the one hand, our findings are consistent with established theories such as the role of neurotransmitters, inflammation, and stress response in delirium (i.e., reported association of acetylcholine, IL-6, CRP, procalcitonin, and cortisol)." (PMID 31263968, 2019). "Higher plasma IL-6 level was associated with the increased risk of delirium (OR 2.77, 95%CI 1.53–5.04, P < 0.01)." (PMID 29669581, 2018). "There appear to be higher levels of IL-6 in patients with delirium and an association between S-100B concentrations and duration of delirium." (PMID 29801516, 2018). "In multivariate analysis, the higher plasma IL-6 was associated with the increased risk of delirium (OR 1.61, 95%CI 1.00–2.58, P = 0.04)." (PMID 29669581, 2018). "Our evaluation of the IL-6 association with postoperative delirium needs careful clinical interpretation." (PMID 28587598, 2017). "A putative mechanism is the high interleukin-6 levels associated with delirium in laboratory animals and humans." (PMID 27711165, 2016). "Conversely, an association of IL-6 and IL-8 cytokines with delirium was found in two different works, focused on medical and surgical patients." (PMID 25368603, 2014). "A postmortem investigation found an association between delirium in older patients and the activity of astrocytes, microglia and IL-6 in the brain." (PMID 24886875, 2014). "Other studies with systemic inflammation, induced by LPS, have implicated IL-6 in the cognitive effects and raised systemic IL-6 has been associated with post-hip fracture delirium." (PMID 23840908, 2013). "In this descriptive study it is surprising to find that lower levels of IL-6 as well as IL-15 were associated with the development of postoperative delirium." (PMID 24093540, 2013). "Extended with the biomarkers TNF-α, IL-6, IL-18, IL-1ra, and IL-10, the 10 best biomarkers associated with delirium (all P < 0.10) were then entered into a multivariate logistic regression analysis." (PMID 22206727, 2011). "IL-6, a pleiotropic cytokine, stands as a sentinel marker of this acute-phase reaction and has been implicated in various neurological and psychiatric conditions, including delirium." (PMID 41229511, 2025). "For example, the -174G/C polymorphism in the IL-6 promoter region influences transcriptional activity and cytokine production, with the high-producing G allele conferring increased delirium risk following cardiac surgery in older patients (odds ratio 2.65, 95% CI 1.54–4.57)." (PMID 41375722, 2025).
delirium (continued). "Despite the well-established association of serum molecules like interleukin-6 (IL-6) with delirium, the translation of these biomarkers into robust predictive models has encountered obstacles, primarily due to delirium’s inherently complex and multi-dimensional characteristics." (PMID 38921436, 2024). "Indeed, several clinical studies have demonstrated strong associations between peripheral IL-6 and delirium/coma in mechanically ventilated patients with acute lung injury." (PMID 38778074, 2024). "However, dexmedetomidine inhibits the MAPK signaling pathway to ameliorate delirium by decreasing IL-6 and IL-8, which are associated with delirium." (PMID 37962460, 2024). "We furthermore found that elevated postoperative S100β, IL-6, and IL-1β concentrations are associated with an increased risk of developing delirium, and interventions reducing their perioperative release may decrease the risk for POD." (PMID 37373482, 2023). "In conclusion, among critically ill patients with delirium, our hypothesis-generating study suggests levels of IL-6 and IL-10 at one week of ICU stay may be associated with mortality." (PMID 37656731, 2023). "Different proofs have linked elevated levels of the interleukins IL-6 and IL-8 to delirium." (PMID 38131687, 2023). "Moreover, elevated IL-6 in association with delirium was similarly found in a study of elderly patients after abdominal surgery." (PMID 38131687, 2023). "Estrogen has been implicated in reducing peripheral IL-6 expression, but it is unknown whether the increased susceptibility of postmenopausal females to developing delirium concomitant with UTIs reflects diminished effects of circulating estrogen." (PMID 36380004, 2022). "Given that IL-6 is significantly upregulated in AKI, future studies are needed to determine whether modulation of the IL-6 signaling pathway mitigates AKI-associated delirium." (PMID 36030220, 2022). "In addition, two large clinical cohort studies reported that plasma IL-6 were increased in delirious patients shortly after surgery and IL-6 levels were significantly associated with an increased risk of postoperative delirium." (PMID 36160165, 2022). "It has been reported that serum IL-6 and 8 levels were associated with delirium severity." (PMID 36077505, 2022). "Moreover, it will be important in future studies to examine the associations of IL-6 with delirium duration and feature severity." (PMID 34044881, 2021). "Mon2 produce IL6 under stimulation, which may possibly explain the association of elevated Mon2 with extracardiac complications such as delirium and AKI after cardiac surgery." (PMID 31969629, 2020). "We confirmed and extended previous studies examining an association between IL-6 and delirium." (PMID 29669581, 2018). "We used conditional logistic regression to model the risk of IL-6 on delirium incidence." (PMID 28587598, 2017). "Ultimately, it is reassuring that the two analytic approaches yielded the same conclusions in terms of a statistically significant association between IL-6 and delirium at POD2, despite yielding different effect measures with different clinical interpretations." (PMID 28587598, 2017). "We hypothesized that if the association between PREOP IL-6 and delirium case was statistically significant at type-I error of 0.05 then we would consider PREOP IL-6 a risk marker." (PMID 28587598, 2017). "While prior studies have demonstrated the role of estrogen in reducing peripheral IL-6 expression, it remains unknown whether the increased susceptibility of postmenopausal females to developing delirium with UTI reflects diminished effects of circulating estrogen on suppressing peripheral IL-6." (PMID 36380004, 2022). "Elevated CRP and IL-6 have been linked to BBB permeability and microglial activation, mechanisms implicated in delirium pathophysiology." (PMID 40889075, 2025).